INS (insulin)
Diseases named in the same sentence as INS in open-access papers (continued):
Sharing a sentence is not in itself a finding about the gene and the disease.
Insulin resistance (continued). "Haffner and colleagues examined the relation between the fasting proinsulin-to-insulin ratio with a number of metabolic disorders believed to be associated with the insulin resistance (IR) syndrome." (PMID 24215809, 2013). "Increased adiponectin levels have been associated with enhanced insulin sensitivity and enalapril markedly attenuated the glucose and insulin resistance in mice in the HF group." (PMID 23894285, 2013). "Patients with T2DM and obese people usually have hyperlipidemia, which can cause insulin resistance and impaired insulin secretion." (PMID 23349838, 2013). "Obesity-associated insulin resistance (IR) is consistently associated with elevated levels of proinflammatory cytokines such as TNFα, IL-6, and IL-1β, and neutralization of TNFα improves insulin sensitivity in obese rodents." (PMID 23577240, 2013). "Enhanced ubiquitination and proteasomal degradation of insulin signalling proteins cause insulin resistance in mouse liver and inhibition of the proteasome is associated with increased insulin secretion." (PMID 24324835, 2013). "Beta cells initially compensate for the insulin resistance associated with obesity by increasing insulin secretion." (PMID 23542897, 2013). "By contrast, a common strategy for combating the insulin resistance that is associated with Type 2 diabetes is treatment with insulin sensitizers which increase tissue glucose uptake." (PMID 24024580, 2013). "In both the ghrelin and the GH studies, insulin resistance was caused by reduced peripheral insulin sensitivity whereas insulin sensitivity of the liver remained unaffected." (PMID 23781325, 2013). "In contrast, loss-of-function mutations in p110α impair insulin signalling and cause insulin resistance, inducing a pre-diabetic state." (PMID 23483710, 2013). "Involvement of insulin autoantibodies in insulin resistance has been extensively studied as a mechanism underlying insulin resistance after insulin administration and autoantibodies against insulin have been studied as a marker of type 1 diabetes." (PMID 24106499, 2013). "As emphasized by Ristow and colleagues, treatments for obesity and diabetes with associated insulin resistance are based on the idea that increasing insulin sensitive glucose uptake, with a consequent lowering of blood glucose, will improve health outcomes." (PMID 24024580, 2013). "Increased insulin resistance is implicated by the finding that fasting insulin and glucose intolerance increased in SGLT5-deficient mice under fructose consumption." (PMID 23451068, 2013). "Conversely, after menopause, decreased ovarian estrogen synthesis results in increasing insulin resistance in central adipocytes and higher fasting insulin levels conferring increased risk for metabolic and cardiovascular diseases." (PMID 23061769, 2013). "For example, a newly developed joint meta-analysis approach has recently identified additional loci associated with fasting insulin and other insulin resistance related traits." (PMID 23308243, 2013). "Since a proatherogenic plasma lipid profile and insulin resistance are often associated, we investigated the effects of D76A treatment on insulin sensitivity." (PMID 23936482, 2013). "Impaired function of beta cell will cause deterioration in glucose homeostasis, at this point, insulin secretion cannot keep pace with the underlying insulin resistance and glucose intolerance, then T2DM occurs." (PMID 23671868, 2013). "Beta cell failure with deficient insulin production is the characteristic feature, whilst insulin resistance is only seen in the presence of classical risk factors." (PMID 23766565, 2013). "Obesity causes excess fat accumulation in several tissues in addition to white adipose tissue (WAT), such as other insulin-responsive organs including the skeletal muscle and liver; this predisposes individuals to the development of insulin resistance." (PMID 24321125, 2013).
Insulin resistance (continued). "Activation of NF-κB is a common characteristic of many tumors and is associated with insulin resistance and elevated circulating levels of leptin, insulin, or IGF-1." (PMID 24280167, 2013). "These markers have been shown to be associated with indirect measurements of insulin resistance including fasting insulin levels and HOMA-IR." (PMID 23020992, 2012). "In patients with NAFLD, elevated plasma free fatty acids (FFAs) levels are responsible for insulin resistance causing a decrease in the insulin-stimulated glucose uptake, glycogen synthesis, and PI3K activity in skeletal muscle." (PMID 22110478, 2012). "Compensatory upregulation of antioxidant enzymes under oxidative stress is another risk factor contributing to the development of insulin resistance in view of the high significance of insulin-induced H2O2 for insulin signalling." (PMID 23730255, 2012). "New researches are confirmed the probable role of vitamin D in secretion of insulin and improvement of insulin resistance and even it seems that deficiency of vitamin D is probable factor in metabolic syndrome pathogenesis." (PMID 25246913, 2012). "An altered metabolic state of increased insulin demand, such as obesity which is strongly associated with insulin resistance, confers susceptibility to develop metabolic disease." (PMID 22988521, 2012). "Cytotoxic ceramides cause insulin resistance by activating pro-inflammatory cytokines and inhibiting insulin-stimulated signalling through PI3 kinase-Akt." (PMID 22701480, 2012). "Although evidence points to consider exposure to BPA as a risk factor for insulin resistance, its actions on whole body metabolism and on insulin-sensitive tissues are still unclear." (PMID 22470480, 2012). "Raised insulin levels in children are a marker for insulin resistance, elevated cardiovascular disease risk factors and early atherosclerosis." (PMID 23056434, 2012). "In PCOS patients, leptin positively correlated with BMI,WHR, insulin, and insulin resistance, while ghrelin was only associated with serumtestosterone levels." (PMID 25493169, 2012). "Insulin hypersecretion mostly thought to result from insulin resistance, has also been shown to cause insulin resistance as demonstrated in rodents overexpressing the human insulin gene or treated with exogenous insulin, and by insulin infusion in humans." (PMID 22272304, 2012). "When pancreatic islets progressively fail to enhance production of insulin as compensation for insulin resistance, insulin deficiency, chronic hyperglycaemia and eventually type 2 diabetes will develop." (PMID 22929089, 2012). "Other reported benefits of long-term CR, but not detected in our study, include reduction in fasting glucose and insulin, which are linked to decreased insulin resistance and risk for type 2 diabetes." (PMID 23071718, 2012). "Though cause and effect has not been clearly elucidated, a number of areas of dysfunction within skeletal muscle are related to the disruptions caused to the insulin signaling cascade and ultimately to the degree of insulin resistance." (PMID 22474580, 2012). "These measures were serum levels of fasting insulin (as an assessment of insulin resistance), hsCRP (as an assessment of underlying inflammation) and uric acid (as an assessment of oxidative stress)." (PMID 23062212, 2012). "Elevated PAI-1 levels seem also to have a direct causal role in insulin resistance, since insulin sensitivity was enhanced significantly in obese mice lacking PAI-1 (high-fat/high-carbohydrate diet induced)." (PMID 22272381, 2012). "It has been suggested that age-associated insulin resistance is partly due to diminished function of insulin signaling proteins." (PMID 24764512, 2012). "These hormones are known to cause increased hepatic glucose production, inhibition of insulin release, and peripheral insulin resistance, all of which cause a decrease in the model-based SI metric used in this study." (PMID 22703645, 2012).
Insulin resistance (continued). "Here, we report latent associations between low serum amylase and plasma insulin, insulin resistance, and obesity-related parameters." (PMID 22748134, 2012). "In type 2 diabetes, these same cells fail to increase insulin secretion to compensate for peripheral insulin resistance leading to relative insulin deficiency." (PMID 22253604, 2012). "A second trial showed improvement in insulin sensitivity and decreased fasting insulin levels in 81 vitamin D deficient subjects with baseline insulin resistance given 4,000 i.u." (PMID 22462011, 2012). "Insulin resistance in this model was due to lipid-induced defects in the insulin signaling pathway that was caused by a reduction in tyrosine phosphorylation of IRS1, increasing its phosphorylation in serine-307 residue." (PMID 22360800, 2012). "Subsequently, AD was shown to be associated with brain insulin resistance and insulin deficiency, with significant abnormalities in the expression of genes and activation of kinases that are regulated by insulin and insulin-like growth factor (IGF) signaling." (PMID 22329651, 2012). "To elucidate the mechanisms by which LYRM1 is involved in the pathogenesis of obesity-associated insulin resistance, we characterized how this gene is regulated by factors that modulate insulin sensitivity." (PMID 22110480, 2012). "In the treatment of type 2 diabetes, β-cell dysfunction and insulin resistance are both associated with higher demand for exogenous insulin." (PMID 22720003, 2012). "Insulin resistance is a major risk factor for developing type 2 diabetes, which is caused by the inability of insulin-target tissues to respond properly to insulin, and in whose aetiology mitochondrial dysfunction is thought to play a crucial role." (PMID 22353542, 2012). "Metabolic syndrome, which can include weight gain and central obesity, elevated serum insulin and glucose, and insulin resistance, has been strongly associated with breast cancer recurrence and worse outcomes after treatment." (PMID 23050155, 2012). "Type 2 (or non-insulin-dependent or adult-onset) diabetes (T2D) which is the more prevalent form, is caused by reduced insulin release, peripheral insulin resistance, and insulin failure to suppress glucose production." (PMID 23024780, 2012). "Higher levels are associated with insulin resistance at the level of lipogenesis and insulin-induced antilipolysis in adipocytes." (PMID 22272381, 2012). "TNF-α is a cytokine expressed by both macrophages and adipocytes and is known to induce insulin resistance associated with hyperinsulinemia by impairment of insulin action on peripheral glucose uptake and hepatic glucose output." (PMID 23056223, 2012). "In ad libitum fed animals, serum leptin, insulin, and glucose were significantly increased in mice deficient in SP-D, and indicative of insulin resistance." (PMID 22509382, 2012). "Healthy pancreatic β-cells display a dramatic response to nutrients and to obesity-associated insulin resistance through hypersecretion of insulin to maintain energy homeostasis." (PMID 21977023, 2012). "Both isolated impaired fasting glucose (IFG) and impaired glucose tolerance (IGT) are characterized by insulin resistance and impaired insulin secretion and insulin resistance constitutes a major cardiovascular risk factor in diabetic and obese patients." (PMID 23153108, 2012). "The association between obesity and insulin resistance is well established and there is evidence that insulin and insulin-like growth factors are involved in the development of breast cancer." (PMID 23113882, 2012). "The high prevalence of PCOS observed in certain ethnic groups also seems to be identified with a high risk of insulin resistance, and certain drugs used to improve insulin sensitivity have been included in the treatment for these women." (PMID 22778733, 2012). "An increase in insulin production and secretion associated with an increased glycemia is a characteristic of insulin-resistance." (PMID 22567167, 2012).
Insulin resistance (continued). "Adiponectin is inversely associated with obesity and insulin resistance and also it stimulates insulin sensitivity of peripheral tissues." (PMID 23213569, 2012). "Insulin resistance likely causes an increase in the efferent arteriolar pressure due to decrease of noradrenaline-induced efferent arteriolar constriction by insulin." (PMID 22523674, 2012). "Some studies showed that there was a positive association between depressive disorder and insulin resistance due to dysregulation of insulin secretion or insulin receptor signaling." (PMID 22348066, 2012). "Results of tissue culture studies suggest that arsenite and/or its methylated trivalent metabolites cause insulin resistance in adipocytes by inhibiting insulin signaling and insulin-activated glucose uptake." (PMID 22889723, 2012). "At baseline all CKD patients exhibited high adiponectin values positively associated with insulin and insulin resistance." (PMID 22537670, 2012). "That subtle inflammation, including critical expression of TNF-α, is associated with and likely causal for obesity linked T2D insulin resistance and faulty insulin signaling is well appreciated." (PMID 22606220, 2012). "Acrylamide Hb adduct levels in adults were associated with decreased serum insulin and reduced insulin resistance." (PMID 23092936, 2012). "High-GI diets have been linked to insulin resistance in epidemiological observations, whereas low-GI diets improved insulin sensitivity in patients with T2DM." (PMID 24278690, 2012). "In humans, GH/IGF-I secretion and insulin sensitivity decline with aging and insulin resistance is associated with increased morbidity and mortality." (PMID 22983440, 2012). "A correlation between metabolic demand and insulin stimulated glucose uptake is well established as increasing metabolic demand can compensate for underlying insulin resistance." (PMID 22276152, 2012). "Metformin caused a significant decrease in weight (p=0.027), insulin level (p=0.043), and insulin resistance (p=0.048)." (PMID 25246913, 2012). "In this cross-sectional study, we found that total physical activity mainly composed of occupational activity, was strongly inversely associated with fasting insulin and insulin resistance." (PMID 22455464, 2012). "PCOS is associated with defects in insulin activity, where a high percentage of patients present symptoms of insulin resistance (IR), often associated with hyperinsulinemia." (PMID 22390153, 2012). "Both insulin resistance and inadequate insulin secretion are considered as possible causes of the increased risk of DM2." (PMID 22927833, 2012). "There was, however, a strong association between serum chromium and change in insulin resistance (β = -0.83, p=0.01), where subjects with the highest serum chromium had a worsening of insulin sensitivity." (PMID 23194380, 2012). "Clinical and metabolic variables were determined to be associated with insulin resistance or insulin sensitivity based on the δ13CO2 from the breath test, with a cut-off point of 9.99‰." (PMID 22848216, 2012). "Fatty liver disease (FLD) is commonly associated with insulin resistance and obesity, but interestingly it is also observed at low insulin states, such as prolonged fasting." (PMID 22745692, 2012). "To get insight into molecular mechanisms underlying insulin resistance, we compared acute in vivo effects of insulin on adipose tissue transcriptional profiles between obese insulin-resistant and lean insulin-sensitive women." (PMID 22471940, 2012). "Insulin resistance is a major risk factor of T2D and refers to a state in which physiological concentrations of insulin are poorly effective." (PMID 22978376, 2012). "Although development of insulin resistance is likely to involve loss of the regulatory actions of insulin on hepatocellular carbohydrate, protein, and lipid anabolism, FA and TAG biosynthesis is preserved." (PMID 23304111, 2012).
Insulin resistance (continued). "The increase in free fatty acids (FFAs) due to obesity causes insulin resistance and, as a consequence, pancreatic beta cells secrete more insulin to compensate for insulin resistance and maintain normoglycemia." (PMID 22474424, 2012). "Given that IL-10 has been found to protect against diet-induced insulin resistance and to be positively associated with insulin sensitivity, we measured this cytokine in the plasma." (PMID 22470484, 2012). "In the present study we compared the acute in vivo effects of insulin on adipose tissue transcriptional profiles of obese insulin-resistant and lean insulin-sensitive women, to gain insight into the molecular mechanisms underlying insulin resistance." (PMID 22471940, 2012). "The insulin resistance, defined as an impaired responsiveness of the body to insulin, is a prediabetic stage associated with obesity, leading to type 2 diabetes." (PMID 23065486, 2012). "Morbid obesity is associated with insulin resistance and marked insulin hypersecretion, but the function of β-cell is preserved." (PMID 23133447, 2012). "Skeletal muscle insulin resistance occurs at a late point in the insulin signaling cascade and is associated with IMCL and NAFLD severity." (PMID 22359625, 2012). "Insulin resistance is caused by the inability of tissues to respond to insulin and the deficient secretion of insulin by pancreatic beta cells." (PMID 22550485, 2012). "Adiponectin, IGFBP-1and triglycerides have been implicated in the pathophysiology of obesity-related insulin resistance, glucose intolerance, and insulin-mediated lipoprotein metabolism." (PMID 23186039, 2012). "The concept that Aβ toxicity causes insulin resistance, and the opposing argument that brain insulin resistance with attendant oxidative stress and neuro-inflammation promotes Aβ accumulation and toxicity are both supported by experimental data." (PMID 22329651, 2012). "The etiology of Type 2 diabetes mellitus is associated with insulin resistance in peripheral tissues or insufficient secretion of insulin in pancreas β cells." (PMID 22942720, 2012). "In summary, the decrease in blood glucose level mediated by FMC was associated with a significant reduction in insulin resistance, as revealed by the plasma insulin content and blood glucose levels in vivo in a KK-Ay mouse model of T2DM." (PMID 22969823, 2012). "Alleviation of inflammation has been identified as an important mechanism in the insulin-sensitizing effects of berberine because of the increasingly evident causative relationship between inflammation and insulin resistance." (PMID 22880019, 2012). "Muscle fibre type and oxidative capacity have been linked to obesity and insulin resistance with a higher percentage of type 1 being positively related to insulin action and inversely with obesity." (PMID 21904680, 2012). "Chronic increase of insulin levels (hyperinsulinemia) causes insulin resistance, preventable by rapamycin." (PMID 22683661, 2012). "We also observed that values of HOMA-IR, a surrogate marker of insulin resistance were lower in subjects with Lp(a) levels >46 mg/dl, suggesting that extremely high levels of Lp(a) are associated with less resistance to insulin." (PMID 22748161, 2012). "Osteocalcin deficiency in knockout mice leads to decreased insulin and adiponectin secretion, insulin resistance, higher serum glucose levels, and increased adiposity." (PMID 23251132, 2012). "Recent studies have shown that preptin enhances insulin secretion in rats, and there is a potential association between preptin and insulin resistance in humans." (PMID 22309801, 2012). "Accordingly, several risk factors associated with elevated serum glucose, including elevated insulin and insulin resistance, have been associated with increased recurrence and worse outcomes." (PMID 23050155, 2012).